TFCP2L1 (transcription factor CP2 like 1)
Description:
Transcription factor that facilitates establishment and maintenance of pluripotency in embryonic stem cells (ESCs). With KLF2, acts as the major effector of self-renewal that mediates induction of pluripotency downstream of LIF/STAT3 and Wnt/beta-catenin signaling (By similarity). Required for normal duct development in the salivary gland and kidney (By similarity). Coordinates the development of the kidney collecting ducts intercalated (IC) and principal (PC) cells, which regulate acid-base and salt-water homeostasis, respectively (By similarity). Regulates the expression of IC genes including subunits B1 and D2 of the V-ATPase complex, OXGR1, CA12, SLC4A1, AQP6 and IC-specific transcription factor FOXI1 (By similarity). Also regulates the expression of JAG1 and subsequent notch signaling in the collecting duct (By similarity). JAG1 initiates notch signaling in PCs but inhibits notch signaling in ICs (By similarity). Acts as a transcriptional suppressor that may suppress UBP1-mediated transcriptional activation (By similarity). Modulates the placental expression of CYP11A1.
Synonyms: CRTR1; LBP9; LBP-9
Tractability: PROTAC: ubiquitination databases record sites on it.
Gene: Protein-coding gene on chromosome 2 (121,216,587 to 121,285,202, reverse strand). Ensembl gene ENSG00000115112.
Subcellular location: Nucleus
Subcellular location (Human Protein Atlas): Nucleoli fibrillar center; Mitochondria
Gene Ontology:
Molecular function: RNA polymerase II cis-regulatory region sequence-specific DNA binding; sequence-specific double-stranded DNA binding; DNA-binding transcription activator activity, RNA polymerase II-specific; DNA-binding transcription factor activity, RNA polymerase II-specific; DNA-binding transcription factor activity; RNA polymerase II transcription regulatory region sequence-specific DNA binding; transcription cis-regulatory region binding
Biological process: regulation of transcription by RNA polymerase II; positive regulation of transcription by RNA polymerase II
Cellular component: nucleus; chromatin; cytoplasm; membrane
Genetic constraint (gnomAD): Loss-of-function variants: 12 observed, 70.29 expected, observed/expected ratio (o/e) 0.17, 90% interval 0.11 to 0.28. The upper end of that interval is the gene's LOEUF score, 0.28, which puts it in group 1 of 6, group 1 being the genes least tolerant of losing a copy. Missense variants: 486 observed, 624.55 expected, observed/expected ratio (o/e) 0.78, 90% interval 0.72 to 0.84. Synonymous variants: 260 observed, 256.61 expected, observed/expected ratio (o/e) 1.01, 90% interval 0.92 to 1.12.
Homologues: Orthologues: chimpanzee TFCP2L1 (99% identical), macaque TFCP2L1 (97% identical), pig TFCP2L1 (96% identical), guinea pig TFCP2L1 (94% identical), rat Tfcp2l1 (94% identical), mouse Tfcp2l1 (94% identical), rabbit TFCP2L1 (91% identical), dog TFCP2L1 (91% identical), tropical clawed frog TFCP2L1 (73% identical), zebrafish tfcp2l1 (66% identical), Drosophila melanogaster gem (46% identical), Caenorhabditis elegans grh-1 (21% identical). Paralogues in human: TFCP2 (73% identical), UBP1 (66% identical), GRHL3 (25% identical), GRHL1 (25% identical), GRHL2 (24% identical).